RN7SL744P (RNA, 7SL, cytoplasmic 744, pseudogene)
Gene: Miscellaneous RNA gene on chromosome 12 (54,344,610 to 54,344,876, forward strand). Ensembl gene ENSG00000264028.
Homologues: Orthologues: chimpanzee Metazoa_SRP (99% identical), macaque Metazoa_SRP (73% identical). Paralogues in human: Metazoa_SRP (78% identical), RN7SL275P (77% identical), RN7SL619P (76% identical), RN7SL376P (74% identical), RN7SL488P (74% identical), RN7SL560P (73% identical), Metazoa_SRP (72% identical), RN7SL339P (69% identical), RN7SL784P (69% identical), RN7SL377P (68% identical), RN7SL48P (68% identical), RN7SL644P (67% identical), and 702 more.